IL6 (interleukin 6)
Diseases named in the same sentence as IL6 in open-access papers (continued):
Sharing a sentence is not in itself a finding about the gene and the disease.
nosocomial infection (22 papers, 2007 to 2025). An infection acquired in a hospital or other healthcare setting. "The combined use of IL-6 and IL-18 levels at 0 hours postoperatively significantly improved the prediction of nosocomial infection." (PMID 36299462, 2022). "In the ROC analysis, the AUC for prediction of nosocomial infection using a combination of IL-6 and IL-18 at POD1 was 0.9616, while the AUCs for IL-6 alone and IL-12 alone were 0.8584 and 0.8256, respectively." (PMID 36299462, 2022). "This indicated that the combination of early IL-6 and IL-18 levels was a good predictor of postoperative nosocomial infection in abdominal surgery recipients." (PMID 36299462, 2022). "Elevated interleukin 6, elevated ultrasensitive C-reactive protein, and decreased platelet count are potential biomarkers for predicting the prognosis of patients with ECMO-associated nosocomial infections." (PMID 40104588, 2025). "The introduction into the routine practice of indicators such as PCT and IL-6 may provide an opportunity for timely diagnosis, the optimization of the therapeutic approach and the reduction in complications from nosocomial infections." (PMID 37755410, 2023). "Thus, these three inflammatory factors (IL-6, IL-12, and IL-18) are involved in the activation of the inflammatory response and are elevated in the early stages of nosocomial infection." (PMID 36299462, 2022). "According to the comparisons, we found significant differences in IL-6, IL-12, and IL-18 levels between the M-NI and M-NNI groups, which might be associated with the occurrence of postoperative nosocomial infections." (PMID 36299462, 2022). "The ROC curve further provided evidence that the combination of IL-6 and IL-18 could better predict the occurrence of postoperative nosocomial infection." (PMID 36299462, 2022). "While requiring confirmation in a larger cohort, the current data indicate the potential utility of cerebrospinal fluid biomarker strategies to identify differential initiation of a common downstream interleukin-6 pathway to diagnose nosocomial infection in this challenging clinical cohort." (PMID 33409494, 2020). "In this retrospective study, the high levels of IL-6 and IL-10 in non-survivors were measured, and we identified that the nosocomial infection after PICU admission was an independent risk factors for all-cause hospital mortality." (PMID 32772917, 2020). "Additionally, increased IL-6 values were an indicator of the development of a nosocomial infection in trauma patients." (PMID 19781105, 2009). "This indicated that high levels of IL-6 and IL-10 in non-survivors could provide an insight for adenovirus-associated nosocomial infection." (PMID 32772917, 2020). "For example, it is well-established that IL-6, IL-8, IL-10, and MCP-1 (CCL2) are elevated early after injury and are correlated with adverse outcomes including nosocomial infection, multiple organ dysfunction syndrome, and mortality." (PMID 36532045, 2022). "In addition, the circulating levels of five cytokines, IL-10, IL-15, IL-6, IL-8, and TNF alpha, were measured for each patient, and the results showed that patients with nosocomial infection had significantly increased IL-10 levels at RCC admission." (PMID 38426112, 2024). "One-way logistic regression analysis showed that IL-6 (OR: 1.02, 95% CI: 1.01–1.03; p = 0.001), hs-CRP (OR: 1.59, 95% CI: 1.02–2.47; p = 0.041), and Plt (OR: 1.01, 95% CI: 1.01–1.02; p = 0.031) were important factors affecting the prognosis of ECMO-related nosocomial infections." (PMID 40104588, 2025). "The exclusion criteria included concomitant infection during progression; therefore, none of the patients included in our study showed clinical, analytical, or radiological changes attributable to nosocomial infection, and the differences in IL-6 levels could not be attributed to this circumstance." (PMID 37147677, 2023).
pneumococcal pneumonia (22 papers, 2011 to 2024). A febrile disease caused by STREPTOCOCCUS PNEUMONIAE. "IL-6 gene-deficient mice are insensitive to pneumococcal pneumonia following intranasal inoculation of Streptococcus pneumonia." (PMID 25889862, 2015). "In a study by Endeman and colleagues, the levels of pro-inflammatory cytokines (IL-1 receptor antagonist, IL-6, IL-8 and IL-10) were found to be influenced by the nature of the causative microorganisms, with pneumococcal pneumonia being significantly associated with higher levels." (PMID 34071031, 2021). "Deletion of UGRP1 or blocking UGRP1 interaction with PDPN protected mice against S. pneumoniae‐induced severe pneumococcal pneumonia, and activating RhoA with agonist in UGRP1‐deficient mice restored the reduced IL‐6 production." (PMID 35652821, 2022). "Compared with other cytokines, IL‐6 shows more inflammatory effect and correlates prominently with death rates in the patients with severe pneumococcal pneumonia." (PMID 35652821, 2022). "During pneumococcal pneumonia in mice, high levels of IL-6, IL-1β and TNF-α are produced in the early stages of lung parenchyma and/or bronchoalveolar space infection." (PMID 34925324, 2021). "In studies focused on IL-6 and S. pneumoniae infection, IL-6 levels were elevated and these elevated IL-6 were protective to the host defending against pneumococcal pneumonia by down-regulating the activation of the cytokine network." (PMID 32038632, 2019). "On the other hand, IL-6 contributes to host defense against pneumococcal pneumonia through downregulating activation of the cytokine network in the lung." (PMID 26289430, 2015). "Furthermore, in a model of pneumococcal pneumonia, IL-6–/– mice showed six times more pneumococci in the lung tissue and a higher mortality than wild-type mice." (PMID 34295313, 2021). "Our results indicate that IL-6 resists secondary pneumococcal pneumonia in several different ways." (PMID 32038632, 2019). "Indeed, sustained high levels of TNF-α, IL-6 and IFN-γ are associated with increased disease severity during pneumococcal pneumonia." (PMID 27973447, 2016). "GMCSF is known to improve lung immunity by accelerating bacterial clearance and neutrophil recruitment while IL-6 contributes to lung defense by orchestrating the pro- and anti-inflammatory cytokine network, thus emphasizing the relevance of this study to the pathogenesis of pneumococcal pneumonia." (PMID 27597997, 2016). "We also assessed BALF levels of other important pro-inflammatory mediators during pneumococcal pneumonia such as TNF-α, IL-6 and CCL2." (PMID 37275853, 2023). "We also found that children with SBI had significantly higher IL-6 levels when compared with those with VI, NPI and controls, with the highest value observed in the only patient with confirmed pneumococcal pneumonia." (PMID 34344349, 2021). "Since cytokines are important regulators of the host immune response during pneumococcal pneumonia we measured levels of the following cytokines in lung homogenates and plasma: TNF-α, IL-6, IL-10, IL-12p70, IFN-γ, MCP-1 and KC." (PMID 25366058, 2014). "Serotype 11a (M10) murine pneumococcal pneumonia resulted in an early local levels of TNF-α and IL-6 in the pulmonary compartment, whereas serotype 3 (ATCC6303) displayed a more delayed response, which remained until death occurred." (PMID 21483672, 2011). "Moreover, IL-6 and IFN-γ knockout mice showed impaired defense against pneumococcal pneumonia and demonstrated higher mortality." (PMID 29922273, 2018).
schistosomiasis (22 papers, 2012 to 2026). An infectious disease caused by parasitic trematodes of the genus Schistosoma that colonize human blood vessels and release eggs that can cause granulomatous reactions leading to acute (swimmer's itch or acute schistosomiasis syndrome) or chronic disease. "This preliminary study with a limited number of patients suggested that CYP2D6 *5/*5 and IL6-174C polymorphisms has an effect on severity and morbidity of schistosomiasis." (PMID 29182577, 2017). "The IL6-174C variant was found in 2 of 15 (13.3%) schistosomiasis-haematobia-infected patients." (PMID 29182577, 2017). "Regarding IL-6, our results showed that schistosomiasis resulted in high expression of IL-6 which was significantly reduced in mice pre-infected with T. spiralis." (PMID 39439825, 2024). "Cytokines such as TNF-α, IL-1β, IL-6, IL-4, and IL-10, among others, show increased serum levels during schistosomiasis, reflecting the polarization and complexity between Th1 and Th2 immune responses." (PMID 38239348, 2023). "Cytokines, such as TNF-α and IL-6, play an essential role in the progression of the schistosomiasis." (PMID 33553120, 2020). "Mice in the model group exhibited high TNF-α and IL-6 protein levels owing to schistosomiasis-induced liver tissue damage." (PMID 33553120, 2020). "Cytokines such as TNF-α, IL-6, and IL-1 β, which are significant mediators of tissue damage, play an essential role in the progression of schistosomiasis." (PMID 33553120, 2020). "The cytokine levels of TNF-α, IFN-γ, IL-6, IL-4, IL-5, IL-10, IL-13, and IL-17A in the sera of acute phase schistosomiasis were all significantly increased in the IUT and VEH groups compared with the UI group." (PMID 30258438, 2018). "IL-6 has been demonstrated to have an anti-inflammatory role in schistosomiasis, down-regulating TH-1 responses by inducing the expression of IL-10 which in turn down-regulates expression of INF-γ." (PMID 23840855, 2013). "This suggests that IL6 may play a role in the immune response to schistosome eggs and the development of egg-induced immunopathology such as liver granulomas during schistosomiasis." (PMID 38033168, 2023). "This is mainly due to the fact that schistosomiasis is dominated by the Th1 immune response at 6–8 weeks and then reaches a peak, and subsequently, a large number of pro-inflammatory cytokines such as tumor necrosis factor, interleukin-1, and interleukin-6 appear." (PMID 35004354, 2021). "We compared the levels of biomarkers (IL-6, sTREM, eotaxin-1, FABP, sCD23, and LPS) between children with schistosomiasis (detectable eggs) and uninfected children (undetectable eggs)." (PMID 35603171, 2022). "A subtle increase in levels of IL-6, eotaxin-1, FABP, sCD23, and LPS among schistosomiasis-infected children signaled a change in the concentration of these systemic biomarkers during schistosomiasis triggered by an immune response." (PMID 35603171, 2022). "Quantification of inflammatory mediators in liver fragments from a chronic model of schistosomiasis showed a significant decrease in TNF-α, IL-1β (P < 0.01) and IL-6 (P < 0.001) levels after cell therapy." (PMID 31015492, 2019). "Similar patterns of immune dysregulation have been observed in other HIV-parasitic co-infections, such as schistosomiasis and soil-transmitted helminths, where elevated TNF-α and IL-6 persist, even in individuals on ART, indicating persistent immune activation." (PMID 40046043, 2025). "A previous study in an area highly endemic for S. haematobium suggested that urinary IL-6 and IL-10 have this potential but not much is known in relation to urinary cytokines and the influential factors in schistosomiasis." (PMID 37018184, 2023). "However, during the chronic phase of schistosomiasis, the levels of TNF-α, IFN-γ, IL-6, IL-4, IL-10, and IL-17A remained increased in the IUT and VEH groups." (PMID 30258438, 2018).
schistosomiasis (continued). "IL-6 can up-regulate IL-10 production upon exposure to S. mansoni eggs in vivo and the two cytokines together negatively regulate IL-12 and IFN-γ production during the early phase of infection, indicating an anti-inflammatory role of IL-6 during schistosomiasis." (PMID 27152725, 2016).
Seizure (22 papers, 2012 to 2025). A seizure is an intermittent abnormality of nervous system physiology characterized by a transient occurrence of signs and/or symptoms due to abnormal excessive or synchronous neuronal activity in the brain. "Research has shown that epileptic seizures are linked to heightened levels of PICs, primarily IL-1β, IL-6, and TNF-α." (PMID 38405667, 2024). "Immunohistochemistry observation revealed the development of seizures along with increased glutamate and decreased GABA (“Interleukin-6-CAUSES-Seizures”)." (PMID 30587224, 2018). "Our results confirm and extend these findings by demonstrating that elevated serum and CSF IL-6 levels in FS patients could be, at least in part, an aetiopathogenetic factor in the manifestation of febrile seizures in susceptible children." (PMID 27068222, 2016). "Likewise, excessive and continuous production of IL-6 during epileptic seizures could be the cause of GADA production." (PMID 37025699, 2023). "In seizure models induced byPTZ, an increase in the levels of IL-1β, IL-6, and TNF-α cytokines in the hippocampus of rats has been reported." (PMID 40969414, 2025). "Increased interictal (time between seizures) serum levels of IL-6 together with IL-1b, IL-1Ra, IL-8, INFy, IFNlambda3 and IL-17 have also been correlated to seizure severity in patients with different types of epileptic seizures." (PMID 36895367, 2023). "Bacteroides genus consists of a group of bacteria capable of regulating the release of inflammatory cytokines such as Interleukin 6 (IL-6) and Interleukin 17 (IL-17) in dendritic cells, which are highly correlated with seizure severity." (PMID 36079829, 2022). "The plasma elevation of proinflammatory cytokines (IL-1; IL-6; TNF-alpha; INF-gamma), which is traditionally associated with epileptic seizures, is countered by the elevation of anti-inflammatory mechanisms (IL-10; Fractalkine; GCSF) and the decrease in plasma concentration of IGF-1." (PMID 40076950, 2025). "Further, our data showed, for the first time, that CBD treatment regulated immunologic responses to seizures by lowering proinflammatory cytokines (IL-33 and IL-6) production and enhancing the level of IC protein of PD-1 within the CNS as well as systemically in the peripheral blood." (PMID 40177581, 2025). "Increased IL-6 production has been showed in patients with refractory epilepsy and experimental models of temporal lobe epilepsy, where in an early rise in IL-6 levels were correlated with acute epileptic seizures onset." (PMID 37008784, 2023). "Data from FLE patients have been included in previous studies but merged with other focal seizures in the heterogenous group of XTLE patients for which both increased and unchanged IL-6 levels have been reported." (PMID 36895367, 2023). "In this study, we found that IL-6 and TNF-α serum levels were significantly higher in FS patients than in febrile children without seizures, and IL-6 and TNF-α levels positively correlated with the serum levels of IL-1β in children with FS." (PMID 38218765, 2024). "Seizure, neuronal apoptosis, oxidative stress (increased SOD and GSH-Px expression and decreased MDA and 8-OHdG expression) and inflammation (reduced IL-1β, TNF-α, and IL-6 expression) were reduced by miR-485 in epileptic cells." (PMID 34021541, 2021). "Therefore, we infer that the anticonvulsive effect of UR, RP, and VA—at least for proinflammatory cytokines IL-1β, IL-6, and TNF-α—did not play a key role in the KA-induced acute seizure." (PMID 24381640, 2013). "Thus, in the current report we examined the effects of inhibiting microRNA‐155 (miR‐155) on the levels of IL‐1β, IL‐6 and TNF‐α, and expression of GAT‐1 and GAT‐3 in the parietal cortex, hippocampus and amygdala of rats with nonconvulsive seizure (NCS) following cerebral ischaemia." (PMID 31144434, 2019).
uremia (22 papers, 2013 to 2024). A clinical syndrome associated with the retention of renal waste products or uremic toxins in the blood. "Possibly, a vicious cycle of inflammation during uremia leads to the predictive effect of cytokine release and cardiovascular death as shown for Saa and Il-6." (PMID 35916902, 2022). "Adipose cells exposed to uremia-primed macrophages showed increased IL-6 and CCL2 expression in the human and murine models." (PMID 33536542, 2021). "Our data postulates that IL-6 is a key cytokine regulating macrophage recruitment to adipose tissue in uremia." (PMID 33536542, 2021). "Differences in ATMS density highlight the necessary role of IL-6 in macrophage infiltration in uremia." (PMID 33536542, 2021). "Traditional inflammatory biomarkers, including CRP, TNF-α, and IL-6, have been found to be predictors of cardiovascular disease and even uremia." (PMID 31427482, 2019). "The increased IL-6 secretion by cells that wereincubated with HD serum suggests a potential effect of uremia in theintestinal inflammatory response." (PMID 29944162, 2018). "O aumento da secreção de IL-6 pelas células incubadas com soroHD (pré e pós) sugere um potencial efeito da uremia sobre a respostainflamatória intestinal." (PMID 29944162, 2018). "Interleukin-6 (IL-6), a marker of inflammation, was significantly elevated in adenine-fed mice with mild and severe uremia compared to controls." (PMID 29593228, 2018). "The serum levels of TNF-α, IL-6, and IL-10 in the uremia group presented an increased trend over time, and these cytokine levels were higher than those in the control group at all the investigated time points." (PMID 27493661, 2016). "Furthermore, owing to the low-grade inflammation, IL-6 has been found to be chronically elevated in uremia." (PMID 36430566, 2022). "One study found that patients with uremia had elevated IL-6, TNF-α, and CRP levels." (PMID 34678995, 2021). "Another study also showed that HD patients with UP had significantly higher serum CRP and IL-6 levels compared to HD patients without UP, UP seems to be associated with an up-regulation of micro-inflammation in uremia." (PMID 33471852, 2021). "These suggest the different effects of uremia and serum IL-6 on CYP450 enzyme." (PMID 30991873, 2019). "Since IL-6 is the cytokine with higher expression changes in the in-vitro adipose tissue cell and macrophage models, we hypothesize that IL-6 has a leading role in macrophage recruitment to adipose tissue in uremia." (PMID 33536542, 2021). "Our data demonstrate that IL6 and TNFα contribute to the activation of HIF and NFκB respectively in uremia." (PMID 33536542, 2021). "The source of increased ATMS in uremia needs to be determined but higher numbers of circulating peripheral monocytes in uremia as well as elevated CCL2 and IL-6 in the cell models suggest a preferential role of monocyte recruitment to adipose tissue." (PMID 33536542, 2021). "In the present study, we also demonstrated that the uremia group presented an increased trend over time in the serum cytokines TNF-α, IL-6, and IL-10, and these cytokines were higher than those in the control group at all the investigated time points." (PMID 27493661, 2016). "Decreasing the production or removing circulating DAMPs in uremia and anti-inflammatory treatments that target the NLRP3 to IL-1 to IL-6 pathway of innate immunity may offer a new paradigm to treat CKD-related PEW and CVD." (PMID 37447158, 2023). "Decreasing the gut production (or increasing the removal) of circulating DAMPs in uremia and/or anti-inflammatory treatments that target the NLRP3 to IL-1 to IL-6 pathway of innate immunity may offer a new paradigm to treat CKD-related PEW and CVD." (PMID 37447158, 2023). "Available data suggest that the anti-inflammatory cytokine interleukin-10 (IL-10) and the major pro-inflammatory cytokines IL-6 (IL-6) and TNF-α may play critical roles in uremia." (PMID 36189322, 2022).
uremia (continued). "Both cell lines exposed to uremia have also a significant increase in the expression of IL-6, TNFα, and CCL2 without changes in expression of anti-inflammatory cytokines." (PMID 33536542, 2021). "Furthermore, we have demonstrated that IL6 plays a key role on HIF activation and TNFα in NFκB activation in uremia." (PMID 33536542, 2021). "The most important is the lack of determination of more serum inflammation (IL-6, IL-10, IL-18, TNF-α), bone metabolic (FGF-23 and bone alkaline phosphatase), and uremia markers." (PMID 36611532, 2022).